PDIA5 (protein disulfide isomerase family A member 5)
Diseases named in the same sentence as PDIA5 in open-access papers (continued):
Sharing a sentence is not in itself a finding about the gene and the disease.
rectum adenocarcinoma (1 paper, 2022). An adenocarcinoma arising from the rectum. "More significantly, the expression level of PDIA5 showed positive correlations with the T cells and macrophages-related immune pathways in BLCA, COAD, GBM, KIRC, KIRP, LGG, and rectum adenocarcinoma (READ), and negative correlations in CESC, LUSC, PRAD, and THCA." (PMID 36003400, 2022).
testicular germ cell tumor (1 paper, 2022). A germ cell tumor arising from the testis. "Conversely, there were negative correlations between PDIA5 and the abundance of CD8+ T cells in some cancer types, like BRCA, HNSC, LUSC, and testicular germ cell tumors (TGCT)." (PMID 36003400, 2022).
uterine corpus endometrial carcinoma (1 paper, 2022). A endometrial carcinoma (disease) that involves the body of uterus. "The mutation rate of PDIA5 was 23%, the majority of the genetic aberrations were missense mutations, and this mutation was more common in uterine corpus endometrial carcinoma (UCEC) than in other cancer types." (PMID 36003400, 2022).
viral infection (1 paper, 2021). "Interestingly, many of the candidate proteins have only limited functional links to viral infection and immune regulation and were not previously known to interact with NAs (e.g., c8orf88, DTYMK, KIF2A, PDAP1, PDIA5, TAOK1, TAOK2, and VRK1)." (PMID 34853303, 2021).
cancer (9 papers, 2018 to 2025). A tumor composed of atypical neoplastic, often pleomorphic cells that invade other tissues. "Subsequently, we explored the effect of PDIA5 on cancer cells and M2 macrophages via a loss-of-function assay." (PMID 36003400, 2022). "Further analysis showed that all of these dysregulated proteins had cancer-related associations, such as PDIA5, DEF6, MZB1, TXNDC5, YARS2, MGST1, and PIH1D1." (PMID 35958927, 2022). "We found that PDIA5 was mainly enriched in cancer cells and macrophages, emphasizing the underlying role of PDIA5 in tumor immunity." (PMID 36003400, 2022). "Mutation and amplification in PDIA5 genes accounted for the majority of alteration frequency in most cancer types." (PMID 36003400, 2022). "Accordingly, inspecting the mechanism underlying PDIA5 promotion of cancer development and drug resistance may contribute to the development of new therapeutic strategies." (PMID 36003400, 2022). "Second, the underlying mechanisms by which PDIA5 takes part in immune regulation remain largely unknown; more loss-of-function assay is necessary to elucidate the specific role of PDIA5 in human cancers." (PMID 36003400, 2022). "Although the pro-oncogene role of PDIA5 in cancers has been reported previously, our study revealed another regulatory effect that PDIA5 plays in GBM cells, through the promotion of the expression of the protein CCAR1." (PMID 39247813, 2024). "The aberrant protein disulfide isomerase A5 (PDIA5) expression was relevant to the poor prognosis of patients with human cancers." (PMID 36003400, 2022). "We also investigated the correlations between PDIA5 expression profiles and drug sensitivity of cancer cell lines from the CTRP and GDSC databases." (PMID 36003400, 2022). "We also performed scRNA-seq to describe the landscape of PDIA5 in cell subpopulations within diverse cancer types." (PMID 36003400, 2022). "This study comprehensively investigated the DNA methylation, genetic alterations, and immune infiltration role of PDIA5 in human cancers based on large-scale bioinformatics analyses and in vitro assays." (PMID 36003400, 2022). "We found that cancer cells and macrophages exhibited high PDIA5 expression in human cancers using the single-cell RNA sequencing analysis." (PMID 36003400, 2022). "In the present study, we comprehensively analyzed the immune infiltration role of PDIA5 in human cancers based on large-scale bioinformatics analyses and in vitro experiments." (PMID 36003400, 2022). "Nevertheless, these observations further highlighted the potentially significant role of PDIA5 in the progression and immune infiltration of human cancers." (PMID 36003400, 2022). "And apparent heterozygous amplification and deletion of PDIA5 were also observed in multiple cancer types." (PMID 36003400, 2022). "And the expression level of PDIA5 was increased as the malignance increased in several cancer types, as evidenced by the differences between LGG and GBM, OPV and OV, and the Gleason scores 6 and 9 of PRAD." (PMID 36003400, 2022). "Our previous findings based on large-scale bioinformatic analysis suggested that PDIA5 expression was elevated in various cancers, but the relevant regulatory mechanism was still unclear." (PMID 36003400, 2022). "These profiles revealed that high PDIA5 expression was involved in the immune infiltration process of human cancers." (PMID 36003400, 2022). "Generally, these findings suggested that cancer cells and macrophages exhibited high PDIA5 expression in human cancers." (PMID 36003400, 2022). "Subsequently, we investigated the role of PDIA5 in the invasion of cancer cells and found that the cell proliferation, colony number, and cell invasion of hepG2, U251, and PC3 cells were impaired by the siRNA-PDIA5." (PMID 36003400, 2022). "Overall, these findings prove that PDIA5 displayed predictive value in the immunotherapy response of human cancers." (PMID 36003400, 2022).
cancer (continued). "Further correlation analyses indicated positive correlations between the mRNA of PDIA5 and CNVs in most cancers." (PMID 36003400, 2022). "To validate the relationships between PDAI5 and immune pathways in cancers, we investigated the effect of PDIA5 on the programmed death-1 (PD-1)/PD-L1 signaling pathway and SPP1 signaling pathway." (PMID 36003400, 2022). "In many cancers, our further analyses suggested that PDIA5 significantly correlated with immunosuppressive cells (including TAMs, fibroblast, and MDSCs)." (PMID 36003400, 2022). "In conclusion, our study provided comprehensive insights into the DNA methylation, genetic alterations, and immune infiltration role of PDIA5 across human cancers." (PMID 36003400, 2022). "Given its various correlations with immune infiltration and complex biological regulation, the regulatory mechanism of PDIA5 in other immune pathways of human cancers need further investigation." (PMID 36003400, 2022). "Since PDIA5 is overexpressed in tumor tissues, we set out to investigate the prognostic value of PDIA5 across cancer types." (PMID 33664747, 2021). "Additionally, PDIA5 exhibited predictive potential for immunotherapy response, highlighting its relevance as a biomarker and therapeutic target for cancer immunotherapy." (PMID 40565099, 2025). "The prognostic significance of PDIA5 mRNA was then evaluated in various cancers." (PMID 39247813, 2024). "Overall, our findings indicated that PDIA5 might be a potential target for immunotherapies in cancers." (PMID 36003400, 2022). "In addition, the number of M2 macrophage markers-CD163 positive cells in most pan-cancer samples was significantly higher than that in para-cancerous tissues, suggesting the potential role of PDIA5 in the recruitment of M2 macrophage in the TME." (PMID 36003400, 2022). "However, the effects of DNA methylation on the cellular levels of PDIA5 in these types of cancers need to be investigated by wet experiments in the future." (PMID 36003400, 2022). "Additionally, PDIA5 also displayed predictive value in the immunotherapy response of both murine and human cancer cohorts." (PMID 36003400, 2022). "In addition, we also observed that high PDIA5 seemed to mediate the resistance to some common chemotherapy drugs in cancer cell lines." (PMID 36003400, 2022). "Besides, the overall alteration rate of PDIA5 was relatively low across human cancers; therefore, the role of DNA methylation and PDIA5 alterations in its function and the occurrence and development of cancer warrants more in-depth exploration." (PMID 36003400, 2022). "Analyzing the role of PDIA5 in the infiltration of immune cells, we observed positive correlations between PDIA5 and macrophages, fibroblast, and myeloid-derived suppressor cells (MDSCs) in the majority of cancers." (PMID 36003400, 2022). "PDIA5 was abundantly expressed in cancer cells of all tumor samples." (PMID 36003400, 2022). "This contradiction may be attributed to the distinct degree of immune cell infiltration in different cancers, and the expression of PDIA5 also varied widely among different cancer types." (PMID 36003400, 2022). "Obvious DNA methylation and moderate alteration frequency of PDIA5 were observed in human cancers." (PMID 36003400, 2022). "Moreover, several studies have confirmed the cancer‐promoting effects of PDIA5 and TXNDC12 as important contributors to cancer progression and chemoresistance." (PMID 32301283, 2020). "Consistent with this hypothesis, previous results have shown that PDIA5 has a critical role in regulating ER stress-dependent ATF6 activation in cancer cells." (PMID 30084354, 2018). "Our study revealed the close relationships between PDIA5 and immune checkpoint genes in multiple human cancers, strengthening the hypothesis that PDIA5 might enhance immunotherapy responses by synergizing with known immune checkpoint inhibitors in cancers." (PMID 36003400, 2022).
cancer (continued). "Our findings suggested that PDIA5 might be a potential target for cancer immunotherapy." (PMID 36003400, 2022). "In addition, PDIA5-high tumors were shown to exhibit a high level of DNA methyltransferases, which indicated the latent ability of PDIA5 to modulate the epigenetic status of human cancers." (PMID 36003400, 2022). "In addition, PDIA5 was closely related to the immune pathways in human cancers." (PMID 36003400, 2022). "In our study, PDIA5 exhibited strong correlations with a stromal score, immune score, and ESTIMATE score in various cancers." (PMID 36003400, 2022). "Based on the correlation analyses between PDIA5 and infiltrated immune cells and other signatures of TME, the present study demonstrated the significant role of PDIA5 in cancer-related immunity." (PMID 36003400, 2022). "For example, macrophages and B cells exhibited high PDIA5 expression in BRCA, while cancer cells and fibroblasts showed high PDIA5 expression in STAD." (PMID 36003400, 2022). "Multiplex immunofluorescence staining showed the upregulated expression level of PDIA5 and the increased number of M2 macrophage markers-CD163 positive cells in pan-cancer samples." (PMID 36003400, 2022). "Therefore, we then analyzed the SNVs and CNVs of PDIA5 and other PDI family members in 33 human cancer types." (PMID 36003400, 2022). "Furthermore, we determined the role of PDIA5 and other PDI members in the classical signaling pathways of human cancer using the GSCALite platform." (PMID 36003400, 2022). "And the correlation analyses indicated negative correlations between the expression level of PDIA5 and DNA methylation in most cancer types." (PMID 36003400, 2022). "Interestingly, in our research, PDIA5 appeared to impact stromal score, immune score positively, and ESTIMATE score in some cancer types, such as BLCA, BRCA, COAD, and GBM, while exhibiting a negative effect on them in PRAD and THCA." (PMID 36003400, 2022). "Therefore, we think that both of PDIA5 and PDIA3 promote the progression of human cancers through affecting the infiltrated immune cells in tumor microenvironment, and the underlying mechanism remains further exploration." (PMID 36003400, 2022). "The immune infiltration in TME promoting the progression of cancers has become increasingly distinguished, but the function of PDIA5 and its impact on the TME were not thoroughly investigated." (PMID 36003400, 2022). "The links between PDIA5 and tumorigenesis in human cancers have not been uncovered previously; we found that PDIA5 expression may be responsible for the regulation of several famous tumor-associated pathways, including the hormone androgen receptor, PI3K/Akt and RKT pathways." (PMID 36003400, 2022).
tumor (7 papers, 2012 to 2025). "In this study, we found that PDIA5 is highly expressed in a variety of tumor tissues and is closely associated with a poor prognosis, particularly in GBM." (PMID 39247813, 2024). "The results indicated that PDIA5 mRNA has significant prognostic value in various tumor types, all associated with a poor patient prognosis, including GBM, LGG, KIRP, LAML, BLCA, KIPAN, PRAD, and KICH." (PMID 39247813, 2024). "Since studies have underlined the critical role of immune checkpoint genes in tumor immunotherapy, we investigate the association between PDIA5 and 47 known immune checkpoint genes." (PMID 36003400, 2022). "The PDIA5 transcriptome expression data in 33 tumor types were analyzed, including tumor sample data from TCGA and normal sample data from GTEx datasets." (PMID 39247813, 2024). "Other studies have also shown that PDIA5 can regulate tumor progression by participating in multiple signaling pathways, such as the PI3K/AKT, the RTK, and the androgen receptor signaling pathways 38-40." (PMID 39247813, 2024). "High levels of PDIA5 expression in macrophages can significantly affect tumor invasion within the immune microenvironment." (PMID 39247813, 2024). "PDIA5 is also involved in several tumor-related regulatory pathways to influence tumor progression, such as the PI3K/AKT, RTK signaling, and androgen receptor signaling pathways 15-17." (PMID 39247813, 2024). "Based on the evidence that PDIA5 showed a positive correlation with TAMs in correlation analyses, we further studied the effect of PDIA5 on tumor invasion and macrophage migration through multiplex immunofluorescence staining and loss-of-function assay." (PMID 36003400, 2022). "The subsequent correlation analyses about the immune subtypes and immune pathways further demonstrated the broad involvement of PDIA5 in tumor immunity regulation." (PMID 36003400, 2022). "PDIA5 was found to be highly expressed in control enhanced (CE) regions, which represented tumor cell infiltration." (PMID 33664747, 2021). "PDIA5 overexpression was also found in the areas of infiltrating tumor cells according to radiology imaging." (PMID 33664747, 2021). "The expression of PDIA5 mRNA was upregulated in most tumor tissues, especially GBM." (PMID 39247813, 2024). "PDIA5 was enriched in various types of immune cells in different tumor samples." (PMID 36003400, 2022). "Altogether, these findings demonstrated that PDIA5 could mediate the invasion of tumor cells and the migration of M2 macrophages." (PMID 36003400, 2022). "Moreover, we also identified several signaling pathways involved in the PDIA5 promoting macrophage infiltration and tumor progression." (PMID 36003400, 2022). "Further loss-of-function experiments with hepG2 cells, U251 cell, PC3 cell, and M2 macrophages demonstrated that PDIA5 could mediate the proliferation and invasion of tumor cells and the migration of M2 macrophages." (PMID 36003400, 2022). "And high PDIA5 levels seemed to suppress the activity of CD8+ T cells and Treg cells in some tumor types." (PMID 36003400, 2022). "PDIA5 regulates the unfolded protein response (UPR) signaling pathway by activating ATF6α, whereby UPR regulates tumor cell survival." (PMID 33664747, 2021).
neurodegenerative disease (1 paper, 2011). A disorder of the central nervous system characterized by gradual and progressive loss of neural tissue and neurologic function. "Association of PDIA5 and BIRC6 (as well as PSMB7 and CYP1B1 in the Salt Lake City population) with POAG indicates that adult-onset glaucoma belongs to the same category of late onset neurodegenerative diseases." (PMID 21655191, 2011).
PDIA5 also shares sentences with these, for which no sentence is quoted: lung squamous cell carcinoma (2 papers); thyroid carcinoma (2); acute myeloid leukemia (1); bladder cancer (1); brain cancer (1); breast carcinoma (1); cervical and (1); CNS tumors (1); endocervical adenocarcinoma (1); endocervical carcinoma (1); esophageal carcinoma (1); infection (1); keratoconus (1); Obesity (1); osteoporosis (1); pheochromocytoma (1); primary angle-closure glaucoma (1); pseudoexfoliative glaucoma (1); sarcoma (1); sarcopenia (1); thymoma (1); uterine cancer (1); uterine carcinosarcoma (1).